PYCARD (PYD and CARD domain containing)
Diseases named in the same sentence as PYCARD in open-access papers (continued):
Sharing a sentence is not in itself a finding about the gene and the disease.
pancreatic ductal adenocarcinoma (3 papers, 2022 to 2024). An infiltrating adenocarcinoma that arises from the epithelial cells of the pancreas. "PYCARD expression was upregulated in the tumor samples and tumor cell lines of pancreatic ductal adenocarcinoma (PDAC) and PYCARD silencing contributed to the cell cycle arrest and decreased cell viability in PDAC." (PMID 36291776, 2022). "In pancreatic ductal adenocarcinoma (PDAC) cells, PYCARD silencing affects CyclinD1, blocking the cell cycle at the G1 phase." (PMID 35745570, 2022).
periodontitis (3 papers, 2024 to 2025). An acute or chronic inflammatory process that affects the tissues that surround and support the teeth. "Patients with polymorphisms in the AIM2 and PYCARD genes reported a susceptibility to periodontitis." (PMID 41440367, 2025). "Alterations in the T and G alleles within the TT, CT, and AG genotypes of the PYCARD gene were significantly associated with periodontitis and coronary heart disease, revealing complex genetic variations in the Iraqi population." (PMID 38813354, 2024). "There was a significant positive correlation between the PYCARD C/T (rs8056505) and BOP, PPD, and CAL in the periodontitis group (P) and the CHD group with periodontitis (AS-P), respectively." (PMID 38813354, 2024). "A significantly positive correlation was also observed between PYCARD A/G (rs372507365) and CAL in the periodontitis group (P) and the CHD group with periodontitis (AS-P), respectively." (PMID 38813354, 2024).
uveal melanoma (3 papers, 2022 to 2025). A melanoma derived from melanocytes of the uveal tract. "Upregulated solute carrier SLC12A9 is associated with aggressive uveal melanoma, while PYCARD encodes an apoptosis-inducing factor and is characteristically suppressed by hypermethylation in aggressive PCa." (PMID 41057544, 2025). "As for DFS (disease-free survival), a higher level of PYCARD expression was only related to a prolonged DFS in UVM (uveal melanoma), while a lower level of PYCARD was correlated with better DFS in LGG." (PMID 36291776, 2022). "In our analysis of the prognostic effect of the expression of AIM2i-RGs, we found that: High expression of the PYCARD showed a good prognosis in BRCA, STAD, and Uveal Melanoma(UVM)and was a protective factor for patients." (PMID 36248785, 2022).
atherosclerosis (2 papers, 2014 to 2025). A disease characterized by the build-up of fatty material and calcium deposition in the arterial wall resulting in partial or complete occlusion of the arterial lumen. "In our study, we utilized several machine learning algorithms to determine that LAPTM5, SLC40A1, TYROBP, CTSB, and PYCARD, which are related to macrophage genes, can act as diagnostic indicators for individuals with atherosclerosis and are linked to immune infiltration in this disease." (PMID 40881888, 2025). "The results demonstrated significantly higher expression levels of LAPTM5, SLC40A1, TYROBP, CTSB, and PYCARD in the serum of atherosclerosis patients compared to the healthy controls." (PMID 40881888, 2025). "Our study highlights the important roles of LAPTM5, SLC40A1, TYROBP, CTSB, and PYCARD in the context of atherosclerosis." (PMID 40881888, 2025). "This study began with analyzing the GSE100927 and GSE23746 datasets to evaluate the expression levels of five key genes—TYROBP, CTSB, PYCARD, LAPTM5, and SLC15A3—in atherosclerosis-affected samples compared to normal controls." (PMID 40881888, 2025).
breast invasive carcinoma (2 papers, 2021 to 2022). "The expression levels of the NLRP3, PYCARD and TLR4 were determined by immunohistochemistry in a cohort of primary invasive breast carcinomas (BCs)." (PMID 34540671, 2021).
breast tumors (2 papers, 2019 to 2020). "Overexpression of DNMT1 (DNA (cytosine-5)-methyltransferase) leads to aberrant hypermethylation of CpG islands in the 5′ untranslated region of PYCARD resulting in PYCARD silencing and recapitulating the transcriptional shutdown observed in numerous primary breast tumors." (PMID 33138274, 2020). "Analysis revealed a significant up-regulation in the expression of genes from the NLRP3 inflammasome pathway (NLRP3, PYCARD, CASP1, and IL-1β) in the stroma of human breast tumours compared with normal stroma, suggesting a functional role for this pathway in tumour progression." (PMID 31558756, 2019).
gastric cancer (2 papers, 2022). A primary or metastatic malignant neoplasm involving the stomach. "In gastric cancer, PYCARD expression was higher in normal tissue than in tumors." (PMID 36291776, 2022). "Hypermethylated TFAP2E, TMS1, PYCARD (ASC/TMS1), and DAPK might be appropriate biomarkers for 5-FU-resistant gastric cancer." (PMID 35309131, 2022).
Lupus (2 papers, 2024). "Thus, circulating PYCARD is a serum biomarker of inflammation and autoimmune diseases such as systemic lupus erythematosus and rheumatoid arthritis." (PMID 39350187, 2024).
pancreatic adenocarcinoma (2 papers, 2022 to 2024). "In pancreatic adenocarcinoma, PYCARD secreted by tumor cells and tumor-associated macrophages (TAMs) stimulated thymic stromal lymphopoietin (TSLP) secretion of fibroblasts in the TME, and high PYCARD and TSLP expressions were linked to worse prognosis." (PMID 36291776, 2022). "Mounting data suggest that PYCARD plays a crucial role in the development and advancement of tumors; for example, in pancreatic adenocarcinoma, 90% of tumor samples show elevated PYCARD expression when compared with adjacent normal tissues, correlating with a poor prognosis." (PMID 39344350, 2024).
periodontal disease (2 papers, 2022 to 2024). "Our findings suggest that the increased frequency of T and G alleles and the distribution of CT, TT, and AG genotypes in PYCARD SNPs are significantly associated with an elevated risk for periodontal disease and CHD." (PMID 38813354, 2024). "This study investigated the association between PYCARD gene polymorphism and susceptibility to periodontal disease and coronary heart disease (CHD) and their correlation with clinical periodontal indices." (PMID 38813354, 2024). "The PYCARD C/T (rs8056505) polymorphism showed a significantly higher frequency of the T allele and the TT genotype in individuals with periodontal disease (P and AS-P groups) compared to the control group (C) group (P values < 0.05)." (PMID 38813354, 2024). "This study investigated the association between variations (polymorphisms) within the PYCARD gene and an increased risk of developing periodontal disease and/or CHD." (PMID 38813354, 2024). "This study investigated the association between PYCARD gene polymorphisms (C/T rs8056505 and A/G rs372507365) and susceptibility to periodontal disease and coronary heart disease in an Iraqi population." (PMID 38813354, 2024). "C allele carriers have a lower chance of contracting both diseases, indicating that the PYCARD C/T (rs8056505) SNP is linked to an elevated risk of periodontal disease and atherosclerotic CHD." (PMID 38813354, 2024). "Therefore, the current study aimed to investigate the relationship between PYCARD SNPs and the risk of developing periodontal disease and/or CHD and to assess the correlation between PYCARD SNPs and clinical periodontal indices." (PMID 38813354, 2024).
rheumatoid arthritis (2 papers, 2024). A chronic, systemic autoimmune disorder characterized by inflammation in the synovial membranes and articular surfaces. "The correlation analysis of PYCARD with IL-38, IL-6, ESR, anti-CCP, and DAS28 showed that PYCAR was correlated with the disease severity of patients with rheumatoid arthritis as well as other inflammatory factors, and played an important role in rheumatoid arthritis." (PMID 38576041, 2024).
thyroid cancer (2 papers, 2013 to 2022). "The PYCARD gene has been found to suppress the proliferation of thyroid cancer cells by inducing apoptosis, which expression was also upregulated in RSC96-KLF6 cells." (PMID 24324791, 2013).
acute T cell leukemia (1 paper, 2020). "Transfection of miRNA-143 in acute T cell leukemia cell line Jurket can up-regulate PYCARD expression, revealing the potential role as ceRNA of PYCARD." (PMID 32751923, 2020).
cardiac arrest (1 paper, 2016). Cessation of breathing and/or cardiac function. "Monocyte TLR2, TLR4, IRAK3, IRAK4, NLRP3, PYCARD and IL1B were initially upregulated in patients following cardiac arrest." (PMID 27260481, 2016).
E. coli infection (1 paper, 2016). "Live E. coli infection also upregulates expression of additional constituents of the innate responses, including CD14, TLR2 and PYCARD, proteins that recognize and orchestrate responses to bacterial infection." (PMID 26933871, 2016).
fungal infections (1 paper, 2024). "NLRP3 functions as a pattern recognition receptor (PRR) that recognizes pathogen-associated molecular patterns (PAMPs) from bacterial, viral and fungal infections among others and that, together with the adaptor ASC/PYCARD protein and caspase-1, form the NLRP3 inflammasome." (PMID 39591118, 2024).
kidney cancer (1 paper, 2022). Primary or metastatic malignant neoplasm involving the kidney. "There were conflicting conclusions about PYCARD expression in kidney cancer." (PMID 36291776, 2022).
liver cirrhosis (1 paper, 2025). "Notably, HBV-miR-2 activated genes including inflammatory genes like P2RX7 and PYCARD, fibrosis-induced genes like ANXA2 and MIF oncogenic genes like FOS and JUN, which were further verified via RT-qPCR and highly expressed in the particular stages of CHB, liver cirrhosis and HCC." (PMID 40405227, 2025).
mild cognitive impairment (1 paper, 2025). "In individuals with mild cognitive impairment (MCI), NLRP3 expression was elevated, but PYCARD or caspase 1 was not, indicating that functional inflammasomes were not assembled." (PMID 40538660, 2025).
myelocytic leukemia (1 paper, 2021). "Apoptosis-associated speck-like protein containing a caspase recruitment domain [ASC; also called PYD- and CARD-domain-containing protein (PYCARD) and target of methylation-induced silencing 1 (TMS1)] reportedly forms aggregates in human myelocytic leukemia HL-60 cells undergoing apoptosis." (PMID 34785680, 2021).
peritonitis (1 paper, 2017). Inflammation of the peritoneum (tissue that lines the abdominal wall and covers most of the organs in the abdomen). "In the peritonitis mouse model, PYCARD, IL-6, and lectin-like oxidized-LDL receptor-1 (LOX-1) were significantly upregulated in epididymal and in subcutaneous adipose tissue at all time points, whereas MCP-1 was induced only in epididymal but not in subcutaneous adipose tissue." (PMID 28428684, 2017).
renal carcinoma (1 paper, 2022). A carcinoma arising from the epithelium of the renal parenchyma or the renal pelvis. "Of note, PYCARD expression was upregulated in renal cancers with high diagnostic ability." (PMID 36291776, 2022).
renal fibrosis (1 paper, 2024). A final common manifestation of a wide variety of chronic kidney diseases characterized by glomerulosclerosis and tubulointerstitial fibrosis. "To verify the expression of PYCARD and Foxp3 on renal fibrosis in vivo, we first established a mouse model of renal fibrosis induced by UUO." (PMID 38343546, 2024).
sarcoidosis (1 paper, 2024). Sarcoidosis is a multisystemic disorder of unknown cause characterized by the formation of immune granulomas in involved organs. "Sarcoidosis unique upregulated DEGs in response to LPS were FOXP1 (Forkhead Box P1), DDIT4 (DNA Damage Inducible Transcript 4), and IL7R, and unique downregulated DEGs in sarcoidosis were PYCARD (Caspase Recruitment Domain-Containing Protein 5), CD4, and PLD3 (Phospholipase D Family Member 3)." (PMID 39284999, 2024).
Sepsis (1 paper, 2022). Sepsis is defined as life-threatening organ dysfunction caused by a dysregulated host response to infection. "Compared to that of healthy individuals, the expression level of AIM2, CASP4, NLRC4, and PYCARD was significantly upregulated, while the expression level of PVJK and PLCG1 was significantly downregulated in both sepsis and septic shock patients." (PMID 36250055, 2022). "Our results showed the expression of AIM2, CASP4, NLRC4, and PYCARD was higher and the expression of PVJK and PLCG1 was lower in both sepsis and septic shock patients than in healthy controls." (PMID 36250055, 2022).
skin cutaneous melanoma (1 paper, 2022). "Twenty types of cancer demonstrated significant correlations with PYCARD expressions, such as ACC, BLCA, SARC, and SKCM (skin cutaneous melanoma)." (PMID 36291776, 2022).
tendinopathy (1 paper, 2025). "For instance, pristimerin, a quinone methide triterpenoid, alleviates tendinopathy by promoting autophagic degradation of AIM2 (absent in melanoma 2) in a PYCARD/ASC (PYD and CARD domain containing/apoptosis‐associated speck‐like protein containing a CARD)‐dependent manner." (PMID 41357670, 2025).
triple-negative breast carcinoma (1 paper, 2022). An invasive breast carcinoma which is negative for expression of estrogen receptor (ER), progesterone receptor (PR), and human epidermal growth factor receptor 2 (HER2). "Furthermore, a reduction of NLRP3 and PYCARD expression has been observed in triple negative breast cancers (TNBCs) with respect to the Luminal phenotypes (p = 0.017 and p = 0.0015, respectively)." (PMID 35745570, 2022).
tumor (59 papers, 2010 to 2026). "Our study tried to reveal the underlying mechanisms of PYCARD in carcinogenesis and provide anti-tumor therapeutic insights into how to increase the efficacy of anti-tumor therapy." (PMID 36291776, 2022). "The silencing of PYCARD is closely correlated with the defective apoptosis of tumor cells, and its reactivation was revealed to increase the susceptibility of tumor cells to cytotoxic agents." (PMID 31086376, 2019). "CASP4, CASP6, CASP8, IL18, and PYCARD were associated with clinical stage, which means that IL18 and PYCARD may be involved in tumor progression." (PMID 36882663, 2023). "In PCa, methylation of PYCARD has also been demonstrated in several tumor cell lines, including LNCaP, LAPC-4, MDAPCa2b, DU145, and PC-3, but not in the benign prostate epithelial cell line BPH-1, or normal prostate epithelial cells." (PMID 37819510, 2023). "For protein level from HPA database, we observed a much stronger staining of PYCARD in three tumor tissues compared to corresponding normal tissues." (PMID 36890219, 2023). "PYCARD, the adaptor protein of inflammasome, plays an important role in tumor carcinogenesis and progression, as confirmed by increasing evidence." (PMID 36291776, 2022). "Our results demonstrated that PYCARD had a close relationship with tumor-infiltrating lymphocytes and potential biomarkers." (PMID 36291776, 2022). "Previous studies have shown that CASP3, CASP9, and PYCARD are involved in tumor invasion and metastasis." (PMID 35845137, 2022). "Here, we confirm the high NLRP3 and PYCARD expression in tumor samples (50% and 31%, respectively) as well as an overexpression of CyclinD1 and MYC, (48% and 32%, respectively)." (PMID 35745570, 2022). "We found that PYCARD was highly expressed in tumor cells, and its expression was positively correlated with renal tumor progression." (PMID 34804944, 2021). "Several studies found that PYCARD was a tumor-inhibiting factor in that it was silenced in many tumor types, and the level of methylation in its promoter was negatively correlated with tumor progression." (PMID 34804944, 2021). "PYCARD, targeted by miR-125a, was shown to be downregulated to different extents in a wide spectrum of human cancers and prevented tumor cells from undergoing apoptosis." (PMID 33014825, 2020). "DNA methylation and histone H3K9 dimethylation are two types of epigenetic modifications contributing to the PYCARD silencing in tumor cells." (PMID 31086376, 2019). "The correlation analysis of immune cell infiltration showed that CASP1, NLRP3, and AIM2, which showed that pyroptosis was involved in the infiltration of immune cells in the tumor microenvironment and NLRP1 exhibited high diagnostic efficacy, while PYCARD demonstrated poor diagnostic efficacy." (PMID 40026444, 2025). "We first compared the differences in protein expression of BAX, CASP1, CASP8 and PYCARD in renal clear cells by CPTAC database, and the results showed that the protein levels of BAX, CASP1, CASP8 and PYCARD were significantly higher than those in normal tissues in tumor cells." (PMID 38439022, 2024). "Furthermore, it has been demonstrated that the expression of PYCARD is correlated with both the response to tumor immunotherapy and prognosis." (PMID 37469408, 2023). "Indeed, it is generally accepted that PYCARD is a pro-apoptotic gene that suppresses tumor growth in many malignancies." (PMID 36291776, 2022). "These contradictory data suggest that the role of PYCARD in BC could depend on the pathological tumor type, stage, molecular profile and tumor microenvironment." (PMID 35745570, 2022). "FAS, BLC2L11, and PYCARD are responsible for the initiation of tumor cell apoptosis." (PMID 35408897, 2022). "Thus, future research should focus on elucidating PYCARD function in tumor growth with advanced technology." (PMID 36291776, 2022). "We observed different NLRP3 and PYCARD expressions in non-tumor vs tumor areas (p<0.0001)." (PMID 34540671, 2021).